TGFBI (transforming growth factor beta induced)
Diseases named in the same sentence as TGFBI in open-access papers (continued):
Sharing a sentence is not in itself a finding about the gene and the disease.
tumor (continued). "Upregulation of HAS2 and MMP-13, in a similar fashion as TGFBI may imply their collective role in tumor progression." (PMID 25369402, 2014). "TGFBI is a TGFβ-induced extracellular matrix protein secreted by the tumor cells and is known to act either as a tumor promoter or tumor suppressor, depending on the tumor environment." (PMID 25369402, 2014). "We observed that DDR1 and TGFBI expression is reciprocal in several tumor cell lines." (PMID 25369402, 2014). "In conclusion, our study not only adds more clarity to how DDR1 may be mediating tumorigenesis, but also supports the tumor suppressor role of TGFBI and suggests that TGFBI may serve as a biomarker for modulators of DDR1." (PMID 25369402, 2014). "We demonstrated that silencing of DDR1 results in an upregulation of TGFBI that could block tumor cell growth and motility, while exogenous addition of TGFBI into tumor cells recapitulated those phenotypes." (PMID 25369402, 2014). "The expression of TGFBI is either down-regulated or lost in a variety of human tumor cell lines." (PMID 22695319, 2012). "Further results derived from in vivo substantiated the role of TGFBI as a tumor suppressor." (PMID 22695319, 2012). "Our previous study has demonstrated that TGFBI-promoted metastasis of RCC cells depends on inactivation of the von Hippel-Lindau (VHL) tumor suppressor and that TGFBI could be a therapeutic target against RCC in the future." (PMID 22950635, 2012). "It is likely that TGFBI protein may function in multiple ways depending on tissue type and tumor microenvironment." (PMID 22695319, 2012). "In this regard, the potential role of TGFBI as a tumor suppressor may provide a novel target for manipulation and therapeutic purposes." (PMID 22695319, 2012). "This is also consistent with a tumor suppressor role for TGFBI." (PMID 22695319, 2012). "To determine whether TGFBI has a tumor-suppressive effect in vivo, we subcutaneously inoculated TGFBI-expressing tumor cells and vector control cells (herein referred as controls) into immuno-deficient nude mice." (PMID 22695319, 2012). "TGFBI was shown to promote metastasis by acting on tumor stroma." (PMID 23077482, 2012). "Additionally, we evaluated the effect of soluble proteolytic fragments of TGFBI on tumor cell survival." (PMID 20509890, 2010). "An earlier study from our laboratory demonstrated a dense methylation pattern of the TGFBI promoter in human tumor cell lines, including both lung (H522, H810, H1417) and prostate (DU145) tumor cell lines, with a complete loss or low level of TGFBI expression in these cell lines." (PMID 18834524, 2008). "It is highly possible that dysregulation of TGFBI expression is tumor cell or type-specific; moreover, TGFBI may be a double-edged sword whose loss or gain of expression may help promote tumorigenesis." (PMID 18834524, 2008). "TGFBI methylation may thus serve as a useful prognostic biomarker, and our optimized MSP method may be useful for evaluation of TGFBI promoter methylation in a wide variety of tumor samples." (PMID 18834524, 2008). "Previous reports have suggested that TGFBI is involved in cell growth, cell differentiation, cell adhesion and apoptosis, and that it may act as a tumour suppressor." (PMID 16457690, 2005). "TGFBI protein is secreted and deposited in extracellular matrix By interacting with integrins, it mediates cell adhesion and migration and thus may regulate tumour growth and angiogenesis." (PMID 38830931, 2024). "However, its role in tumor progression remains controversial and whether TGFBI contribute to malignant behaviors in HNSCC cells has yet to be elucidated." (PMID 38514830, 2024). "Thus, TGFBI acts as a promoter of tumor progression in HNSCC." (PMID 38514830, 2024).
tumor (continued). "It was found that the organoid cultured in vitro could largely maintain the DNA methylation patterns of gene promoter regions as those of in vivo tumor tissues, including the genes BCL2L1, IMPDH2, and TGFBI, which have been reported to be associated with CRC progression." (PMID 37345888, 2024). "Thus, we investigated whether TGFBI could affect metastatic potential by regulating other cell types present in Cat D KO tumor tissues." (PMID 38297161, 2024). "Furthermore, TGFBI may be an effector of the tumor-promoting actions of TGFβ and a potential therapeutic target." (PMID 34561272, 2021). "Moreover, many evidences implicate TGFBI in tumor progression." (PMID 33408771, 2021). "In addition, we explored TGFBI expression across different tumor cell lines in the CCLE database." (PMID 34671645, 2021). "However, as TGFBI is modulated by TGFβ signaling, its tumor promoting or suppressing function could be cell- and context-dependent." (PMID 33408771, 2021). "So far, TNC and TGFBI secretion by TAM has not been linked to tumor cell migration." (PMID 32312959, 2020). "In addition, high expression of TGFBI was correlated to higher tumor stage." (PMID 32406866, 2020). "However, in mesothelioma, breast cancer, and lung cancer, the expression of TGFBI was significantly decreased, so it might act as a tumor suppressor gene 16-18." (PMID 31598162, 2019). "However, a tail vein tumor metastasis model showed that TGFBI knockout could inhibit tumorigenicity and metastasis in vivo." (PMID 31598162, 2019). "Furthermore, TGFBI may act as a tumor suppressor gene, since TGFBI knockout mice develop spontaneous tumors and have upregulated cyclin D1 expression." (PMID 27622658, 2016). "In HNC, TGFBI was validated to be up-regulated in tumor samples, which could promote tumorigenesis." (PMID 26857387, 2016). "Our hypothesis indicates this tumorigenic effect of DDR1 appears to be in part mediated via TGFBI downregulation, which reinforces the notion of a tumor suppressor role for TGFBI We have also demonstrated that exogenous TGFBI could recapitulate the phenotypes associated with DDR1 knockdown." (PMID 25369402, 2014). "Hence, depending on tumor type, TGFBI may show dual activities, either as a tumor promoter or a tumor suppressor and contribute to tumorigenesis accordingly." (PMID 25369402, 2014). "To determine whether the suppressive effects of TGFBI on cell proliferation and subsequent transformation were due to alterations in cell cycle progression, we compared cell cycle profiles between TGFBI-transfected and control cells in these two types of tumor cell lines." (PMID 22695319, 2012). "In this study we did not check for genetic instability but rather precisely reproduced the evidence of TGFBI’s inhibitory effects on cell proliferation, transformation, and G1/S transition using a different model, which strongly supported the conclusion that TGFBI is a tumor suppressor." (PMID 22695319, 2012). "Other genes in the area include PDGFRB, which plays an important role in tumor neovascularization, TGFBI, PTTG1, DOCK2 and DUSP1 (the latter three genes were speculated based on our internal studies), which were likely to be involved in ccRCC progression and development." (PMID 20671976, 2010). "Thus, the percentage of tumor cells in tumor specimens or proportion of tumor cells with TGFBI promoter methylation may be very low in some tumor samples." (PMID 18834524, 2008). "Untreated tumors (model group) exhibited an elevated expression of OTUB1, TGFBI, and VEGF, suggesting their active involvement in tumor angiogenesis." (PMID 40430059, 2025). "The prominence of POSTN, SPARC, and TGFBI among the shared hubs also underscores the role of TGF-β pathway activity and a myofibroblastic stroma in both tumor types." (PMID 40872572, 2025).
tumor (continued). "Cell Adhesion and Migration: CD44, ITGB1, LAMB1, FAT1, PLAUR, and TGFBI are integral to cell–matrix interactions and extracellular matrix (ECM) remodeling, processes critical for tumor invasion and metastasis." (PMID 41303451, 2025). "In our previous study, we demonstrated that the TAMs preferentially secrete TGFBI, which promotes GSC-driven tumor growth through integrin αvβ5-Src-Stat3 signaling." (PMID 39346536, 2024). "To further illustrate the role of TGFBI in the biological function of RCC and the tumor immune process, we investigated the relationship between TGFBI and immune cells, with macrophages and Treg being the top two cells connecting TGFBI expression." (PMID 39068456, 2024). "Given the importance of Cat D in regulating cancer metastasis through TGFBI-mediated TAM polarization, we assessed the clinical importance of Cat D and TGFBI and their possible relationship in human tumor tissues." (PMID 38297161, 2024). "In the tumor tissues, fibrinogen family (FGA/FGB/FGG), mucin 2 (MUC2), and transforming growth factor beta induced (TGFBI) proteins were ranked higher than other tissues." (PMID 39305996, 2024). "We selected TGFBI because this protein is a known TGF-β activity reporter in cancer 34 and its expression is inversely correlated with CD8+ T-cell tumor infiltration." (PMID 38505604, 2024). "Altogether, our data support the idea that Cat D deletion controls TAM polarization from immune-suppressive M2 to immune-stimulatory M1 subtypes through TGFBI and CCL20 secretion, which in turn leads to suppression of tumor metastasis and growth." (PMID 38297161, 2024). "SERPINE1 and TGFBI had the highest increased promoter accessibility and gene expression in EMT tumor clusters (fold change >2)." (PMID 36973268, 2023). "Neutrophils in tumour‐invaded TDLN highly expressed AP (CD74 and HLA‐DPA1/DQA1), pro‐angiogenesis (VEGFA) and immunosuppressive (TGFBI)‐related genes." (PMID 37491740, 2023). "One example is TGFBI, which showed increased promoter accessibility and gene expression in the two EMT tumor clusters." (PMID 36973268, 2023). "The IHC assay further confirmed that protein expressions of VSIG4, TGFBI, and P4HB increased consecutively from normal kidney to renal tumor and then to tumor thrombus." (PMID 37035174, 2023). "The qRT-PCR and immunohistochemistry (IHC) experiments were respectively conducted to evaluate the mRNA and protein expression levels of VSIG4, TGFBI, and P4HB in ccRCC thrombus-tumor-normal tissue triples." (PMID 37035174, 2023). "The eight genes (CAMK2N1, WNT7A, F2RL1, AREG, DEFB1, CNFN, TGFBI, and CAV1) included in the signature have been extensively studied and are known to be involved in tumor progression and EMT process." (PMID 37907576, 2023). "After that, TGFBI secreted by MDMs can also target CD8+ T cells directly, inhibiting its killing effect on tumor cells." (PMID 36761752, 2023). "We found that mesenchymal-related markers such as FN1, TGFBI, and COL1A1 were enriched in mixed-lineage tumor cells." (PMID 35962452, 2022). "Of clinical relevance, TGFBI was enriched in the serum and CSF of GBM patients and significantly decreased after tumor resection." (PMID 35673564, 2022). "Percent tumor burden explained a modest amount of variation in abundance of both CTGF and TGFBI (R2 = 0.18) and slightly less for MYH10 (R2 = 0.16)." (PMID 35422813, 2022). "Percent tumor burden was a significant predictor of CTGF (F = 9.55, p < 0.01), TGFBI (F = 9.41, p < 0.01), and MYH10 abundance (F = 7.96, p < 0.01)." (PMID 35422813, 2022). "The models estimate CTGF, TGFBI, and MYH10 abundances enhance 1.95, 0.54- and 1.13-fold, respectively, for each 1% increase in tumor burden." (PMID 35422813, 2022). "Macrophages are known to promote tumor cell migration through the secretion of proteins, such as EGF, CHI3L1, IGF1, FN1, TNC and TGFBI." (PMID 36551640, 2022).
tumor (continued). "We have previously shown that TAM promote HGSC cell migration by secreting TGFBI, linking the PGI2 -triggered signaling in TAM to altered tumor cell properties." (PMID 36551640, 2022). "Based on the Oncomine and Tumor Immune Estimation Resource (TIMER) databases, TGFBI was upregulated in HCC compared to adjacent normal tissues." (PMID 35265561, 2022). "Consistent with our results, TGFBI plays a tumor-promoting role in CRC, and silencing TGFBI inhibits in vivo tumor growth and in vitro angiogenesis." (PMID 35083181, 2022). "Myosin heavy chain 10 (MYH10), transforming growth factor beta induced (TGFBI) and CTGF were the proteins that correlated best with tumor volume, and their expression levels enhanced as tumor volume increases." (PMID 35422813, 2022). "We explored the correlations of TGFBI expression with TME components, using the ESTIMATE algorithm to calculate the ESTIMATE, stromal, and immune scores in diverse tumor types in the TCGA database." (PMID 34671645, 2021). "Our observation of SNAI2, TGFBI and SERPINE1 in the pEMT signatures of squamous-like cancer types suggests that these signatures reflect both inter-tumour and intra-tumour heterogeneity." (PMID 33972543, 2021). "IHC staining showed that expressions of IGFBP4, TGFBI, and SERPINA10 proteins were detected in para-tumoral normal cells and tumor cells that were mostly located in the extracellular and cytosol compartments." (PMID 34888242, 2021). "Overexpression of TGFBI in Chinese hamster ovary (CHO) cells resulted in a significant decrease in cell growth and tumor-forming ability of these cells in nude mice." (PMID 33912443, 2021). "Tumor growth on CAM and liver metastasis formation in mice were reduced when TGFBI-silenced SW1222 cells were inoculated compared with control SW1222 cells." (PMID 33408771, 2021). "Thus, we explore whether TGFBI could be used as a novel target for tumor immunotherapy." (PMID 34671645, 2021). "More importantly, treating KC cell line-injected C57BL/6 mice with anti-TGFBI-depleting antibody significantly reduced the tumor volume and led to the accumulation of CD8+ T cells to the primary tumor." (PMID 32752017, 2020). "To elucidate the origin of TGFBI, TNC, and FN1 in HGSC ascites, we made use of our transcriptome, proteome, and secretome datasets for tumor cells, TAMs, and TATs7,33." (PMID 32312959, 2020). "Judging from our data, TGFBI seems to have a pro-adhesive effect in HGSC, since primary OCMI cells adhere strongly to rTGFBI, which is accompanied by enhanced tumor motility." (PMID 32312959, 2020). "TGFBI and TNC both bind to integrins and, in case of TNC, additionally to EGF receptors present on the surface of tumor cells, thereby activating migration-inducing pathways." (PMID 32312959, 2020). "We next compared the expression of TGFBI in the different molecular subtypes of the METABRIC database and found that basal and claudin‐low tumours, which are known to contain high percentages of CSCs, have the highest expression levels." (PMID 33080107, 2020). "To identify and quantify the cellular sources of TGFBI, we next isolated by FACS and MACS different cell populations from these tumours and analyse them by qPCR." (PMID 33080107, 2020). "Therefore, it is likely that the four mutated domains of TGFBI are required for its function in trastuzumab response, which is consistent with other studies that described the involvement of FAS1 or RGD motifs in tumor angiogenesis and tumor growth inhibition, as well as in promoting apoptosis." (PMID 31277676, 2019). "Transforming growth factor beta-induced (TGFBI) is an extracellular secreted matrix protein which has been proven to exist in normal and tumor cells." (PMID 31514337, 2019). "Among the eight down-regulated genes, one is an oncogene (NEAT1), six are tumor-suppressor genes (ASS1, PTPRD, ISG15, TGFBI, SELENBP1, MEG3) and one gene serves as both an oncogene and tumor-suppressor gene (CDH17)." (PMID 30563222, 2018).
tumor (continued). "CNA gains of suppressor genes are enlisted by gains of HADAC3 in 18 HRO-, COL18A1 in 16 HRO-, TGFBI in 16 HRO- and CDH4 in 15 HRO tumours." (PMID 28486536, 2017). "MiR-675 promotes tumor progression by suppressing the expression of target genes including Rb, RUNX1, TGFBI, and Twist1." (PMID 29088808, 2017). "There, TGFBI (5q31) was reported to be amplified in 70% of ccRCC cases (7/10) with 5q23.2–q34 gain and CSF1R (5q32) to be upregulated in 30% of tumours (3/10)." (PMID 28486536, 2017). "In esophageal cancer, secreted-TGFBI has been detected in the ECM and tumor vasculature by immunohistochemistry." (PMID 28106769, 2017). "Next, we screened a small panel of tumor cell lines to compare the levels of DDR1 and TGFBI expression by ELISA in order to identify additional models with similar expression profiles as BXPC3." (PMID 25369402, 2014). "BXPC3 tumor xenografts demonstrated reduced growth with DDR1 knockdown, and the same xenograft tumors exhibited an increase in TGFBI expression level." (PMID 25369402, 2014). "Transforming growth factor (TGF)-β-inducible gene-h3 (βig-h3), which also called TGFBI, RGD-CAP, and MP78/70, is widely expressed in various types of tumor cells." (PMID 24595049, 2014). "Previous studies showed that TGFBI/BIGH3 is involved in cell growth, tumor genesis, wound healing, apoptosis, migration, and osteogenesis among others." (PMID 18568131, 2008). "A group of genes, including collagen type I alpha 1 (COL1A1), fibronectin 1 (FN1), laminin subunit gamma 2 (LAMC2), periostin (POSTN), transforming growth factor beta induced (TGFBI), are involved in extracellular mesenchymal organization and affect tumor behavior, akin to our findings." (PMID 40303998, 2025). "MSI analysis revealed significant positive correlations for TACC3 and CXCL1 (p < 0.05), suggesting their potential roles in MSI-high tumor biology, whereas ABCB1, TGFBI, and VDR lacked significant associations with MSI status." (PMID 40791849, 2025). "TGFBI expression is elevated in PDAC, and the downregulation of TGFBI reduces M2 polarization, suppressing macrophage-stimulated tumor growth and enhancing anti-tumor immunity." (PMID 38891952, 2024). "During their expansion from this region to other regions, such as clusters 6 and 3 regions, the tumor cells exhibited a more malignant expression pattern, such as high expression levels of malignant markers, such as TNC and TGFBI, as well as active proliferation markers, such as FOS and WEE1." (PMID 39639005, 2024). "Moreover, Overexpression of TGFBI significantly reduced apoptosis in 786-O and ACHN cells by flow cytometry, which was beneficial to tumor progression." (PMID 39068456, 2024). "The neoepitopes ISSKFKSKR (DDX47) and IEIEDTFETLW (TGFBI) corresponded to category V, and HSTLQKSLW (LRR1) together with KLRKKQNER (SLFN12) neoepitopes corresponded to category TV, being expressed both in VACCIMEL and patient #032’s tumor." (PMID 39840067, 2024). "Both TGFBI and SPP1 were observed to have high average normalized counts within tumor tissues." (PMID 38979413, 2024). "TGFBI, COL3A1, and CXCL12 were significantly upregulated in caf_C1_scissor, which mainly expressed genes characteristic of activated CAF, which secreted pro-inflammatory factors that enhanced EMT and stemness of tumor cells and contributed to tumor metastasis." (PMID 37091977, 2023). "Taken together, these data indicate that many genes distinguish tumor groups with distinct epithelial and mesenchymal features, such as WNT5B, as well as EPB41L4A and TGFBI, controlled epigenetically by an array of transcriptional factors delineated above and chromatin accessibility changes." (PMID 36973268, 2023). "Indeed, three of the four CAF index genes (TGFBI, TGFB2 and FN1) appear in the 938 DEG signature that separates C2 from C1 tumours." (PMID 36207323, 2022).